SYCE3 (synaptonemal complex central element protein 3)
Description:
Major component of the transverse central element of synaptonemal complexes (SCS), formed between homologous chromosomes during meiotic prophase. Required for the assembly of the central element of the synaptonemal complex during meiosis, via remodeling of SYCP1 lattice structures and promoting recruitment of SYCE2-TEX12 and SYCE1-SIX60S1 complexes. Required for chromosome loading of the central element-specific SCS proteins, and for initiating synapsis between homologous chromosomes (By similarity). Chromosome loading appears to require SYCP1 (By similarity). Required for fertility and normal testis development (By similarity).
Synonyms: C22orf41; THEG2
Tractability: No criterion of Open Targets' tractability assessment is met for any kind of drug.
Gene: Protein-coding gene on chromosome 22 (50,551,112 to 50,562,919, reverse strand). Ensembl gene ENSG00000217442.
Subcellular location: Nucleus; Chromosome
Subcellular location (Human Protein Atlas): Golgi apparatus; Nucleoli; Nucleoplasm
Pathways (Reactome):
Reproduction: Meiotic synapsis
Gene Ontology:
Molecular function: protein binding
Biological process: homologous chromosome pairing at meiosis; homologous recombination; reciprocal meiotic recombination; spermatogenesis; synaptonemal complex assembly
Cellular component: central element; chromosome; condensed nuclear chromosome; nucleus; synaptonemal complex
Genetic constraint (gnomAD): Loss-of-function variants: 2 observed, 7.85 expected, observed/expected ratio (o/e) 0.25, 90% interval 0.1 to 0.8. That is too few expected variants to judge how well the gene tolerates losing a copy. Missense variants: 80 observed, 110.42 expected, observed/expected ratio (o/e) 0.72, 90% interval 0.6 to 0.87. Synonymous variants: 36 observed, 40.33 expected, observed/expected ratio (o/e) 0.89, 90% interval 0.68 to 1.18.
Homologues: Orthologues: chimpanzee SYCE3 (99% identical), macaque SYCE3 (98% identical), dog SYCE3 (90% identical), mouse Syce3 (90% identical), rabbit SYCE3 (90% identical), rat Syce3 (89% identical), pig SYCE3 (88% identical), guinea pig SYCE3 (84% identical), tropical clawed frog syce3 (58% identical).
Diseases named in the same sentence as SYCE3 in open-access papers:
SYCE3 is named in the same sentence as 4 diseases in open-access papers, as found by Europe PMC text mining. Sharing a sentence is not in itself a finding about the gene and the disease. The quoted sentences say what the papers report.
infertile (2 papers, 2011 to 2021). "Using the mouse as a model system, we demonstrate that loss of SYCE3 leads to infertility in both sexes." (PMID 21637789, 2011). "Infertility is caused by disruption of meiosis due to the inability of Syce3−/− mice to assemble the central element of SCs." (PMID 21637789, 2011). "Knockout of SYCE3 in mice blocks synapsis initiation and can cause infertility." (PMID 34253240, 2021).
female infertility (1 paper, 2019). Diminished or absent ability of a female to achieve conception. "In addition to this SYCE3 proteins are required for stabilization of the N-terminal region of SYCP1 within the central element of the synaptonemal complex and for synaptonemal complex extension; SYCE3 knockout mice exhibit both male and female infertility." (PMID 31671664, 2019).
male infertility (1 paper, 2024). The inability of the male to effect fertilization of an ovum after a specified period of unprotected intercourse. "Therefore, we hypothesize that the significant downregulation of DEGs (CFAP70, TTC29, CCDC40, DNAAF4, SYCE3, STK36, SPI1 and EMX2) in hybrid yellow catfish is the primary cause of male infertility or reduced fertility." (PMID 38891632, 2024).
SYCE3 also shares sentences with these, for which no sentence is quoted: cancer (1 paper).